TLR2 (toll like receptor 2)
Diseases named in the same sentence as TLR2 in open-access papers (continued):
Sharing a sentence is not in itself a finding about the gene and the disease.
periapical abscess (1 paper, 2021). "Significant higher expression of CYP4F3 (P < 0.0001), VEGF (P < 0.0001), MMP-9 (P < 0.001), IL-8 (P < 0.0001), and TLR2 (P < 0.0001) were noted in the periapical abscess compared with healthy controls." (PMID 34539639, 2021). "CYP4F3, VEGF, MMP-9, IL-8, and TLR2 represented the most upregulated genes in periapical abscess." (PMID 34539639, 2021).
Pleural effusion (1 paper, 2023). The presence of an excessive amount of fluid in the pleural cavity. "Moreover, effusion sTLR2 is significantly elevated and negatively correlated with pleural effusion size, suggesting that it may serve as a decoy receptor and reduce TLR2-mediated inflammation in TBPE." (PMID 36769168, 2023). "Thus, all the current results feature that TLR2 is essential for the production of inflammatory pleural effusion and sTLR2 may serve as a marker for TLR-signaling activation and clinical severity in TBPE." (PMID 36769168, 2023). "Pleural effusion size and pleural fluid levels of vascular endothelial growth factor (VEGF) and soluble TLR2 (sTLR2) in patients with TBPE (n = 36) or transudative pleural effusion (TPE, n = 16) were measured." (PMID 36769168, 2023).
pollen allergy (1 paper, 2012). "Our data show that in a mouse model of birch pollen allergy, perinatal administration of L. paracasei NCC 2461 to pregnant/lactating mothers protects against the development of airway inflammation in offspring by activating regulatory pathways, likely through TLR2/4 signalling." (PMID 22792257, 2012).
pouchitis (1 paper, 2024). Acute inflammation in the intestinal mucosa of the continent ileal reservoir (or pouch) in patients who have undergone ileostomy and restorative proctocolectomy (proctocolectomy, restorative). "The expression of Toll-like receptors (TLRs) is also altered, with a decreased expression of TLR3 and increased expression of TLR5 in normal ileal pouch, and an upregulation of TLR2 expression in pouchitis and upregulation of TLR4 in both normal pouch and pouchitis." (PMID 38929596, 2024).
pregnancy disorder (1 paper, 2013). A disorder that is related to pregnancy. "So far, previous research showed the participation of several single-nucleotide polymorphisms (SNPs) of TLR2, TLR4, and TLR9 in various diseases and pregnancy disorders." (PMID 23161283, 2013). "One possible modification influencing gene function, which was also confirmed in case of TLR2, TLR4, and TLR9 genes in accordance to different diseases and pregnancy disorders, is the occurrence of SNPs within the genetic sequence." (PMID 23161283, 2013).
promyelocytic leukemia (1 paper, 2012). "We were able to demonstrate a down-regulation of TLR2 mRNA expression after treating IL-1β prestimulated IVD cells with curcumin, which confirms findings in other cell types such as monocytic THP-1 cells, HL-60 promyelocytic leukemia cells and primary peripheral blood polymorphonuclear neutrophils." (PMID 22909087, 2012).
prostate tumor (1 paper, 2014). "We showed that, in spite of the absence of surface expression of TLR2 and TLR4, prostate tumor cells are responsive to LPS and LTA implying that activation is mediated through ligand internalization." (PMID 24966802, 2014).
protozoal infections (1 paper, 2023). "Notably, ICAM1, TLR2, and FN1 were associated with bacterial, viral, and protozoal infections, a conclusion also observed in numerous additional studies." (PMID 37233676, 2023).
Psoriasiform dermatitis (1 paper, 2020). A skin abnormality characterized by redness and irritation, with thick, red skin that displays flaky, silver-white patches (scales). "Finally, we intravenously transferred Tregs from WT mice or TLR2 KO mice into TLR2 KO mice to confirm that Tregs caused a difference in imiquimod-induced psoriasiform dermatitis." (PMID 33202847, 2020). "Thus, TLR2 deficiency exacerbated imiquimod-induced psoriasiform dermatitis." (PMID 33202847, 2020). "Thus, the adoptive transfer of Tregs from WT mice ameliorates imiquimod-induced psoriasiform dermatitis in TLR2 KO mice." (PMID 33202847, 2020).
pulmonary arterial hypertension (1 paper, 2025). Pulmonary arterial hypertension (PAH) is a group of diseases characterized by mean pulmonary artery pressure >20 mmHg and elevated pulmonary arterial resistance leading to right heart failure. "Overall, TLR2 plays a significant role in the pathogenesis of pulmonary arterial hypertension by participating in the activation of endothelial cells and vascular smooth muscle cells, thereby contributing to vascular remodeling, and facilitating the development of the inflammatory response." (PMID 41303627, 2025).
pulmonary edema (1 paper, 2020). Accumulation of fluid in the lung tissues causing disturbance of the gas exchange that may lead to respiratory failure. "In this study, we revealed that both inhibition of miR-92a expression and knockout of TLR2 and AP-1 genes could reduce LPS-induced rat ALI, alleviate pulmonary edema, inhibit oxidative stress and inflammatory response, and reduce apoptosis of lung tissue cells." (PMID 33015189, 2020).
renal dysfunction (1 paper, 2023). "Moreover, a strong correlation was evident between the expressions of TLR-4, TLR-2, NF-κB, and TNF-α genes and hepato-renal dysfunction indicators." (PMID 37045926, 2023).
respiratory allergy (1 paper, 2022). "In this work, a vaccine formulation containing allergens from D. siboney HDM and a combination adjuvant with PL of N. meningitides (a TLR2/4 ligand) and Alum was tested in a preventative experimental setting of respiratory allergy in mice." (PMID 36479436, 2022).
retinal dystrophies (1 paper, 2021). "Extracellular release of the nuclear chaperone high mobility group box-1 (HMGB1), a recognized ligand of TLR2 among others, has also been implicated in various retinal dystrophies." (PMID 34360582, 2021). "Elevated expression of some TLRs, including TLR2, has been reported in the retinas of canine models of RP carrying different mutations, and in other non-genetic retinal dystrophies." (PMID 34360582, 2021).
rheumatic diseases (1 paper, 2019). "The polymorphisms rs5743708 for the TLR2 and the rs187084_rs5743836 TLR9 haplotypes appear to be involved in the development of clinical forms of PsA and can be a possible therapeutic target for the rheumatic diseases." (PMID 31781672, 2019).
rheumatic heart disease (1 paper, 2020). An autoinflammatory condition following an infection with Group A Beta Hemolytic Streptococcus (GABHS), in which the heart is attacked by antibodies formed in reaction to a recent GABHS infection. "miR-101 has a role in regulating the immune system by altering the toll-like receptor 2 (TLR2) expression and through this pathway can suppress the immune system in patients with rheumatic heart disease." (PMID 32952941, 2020).
Rickettsiosis (1 paper, 2025). A group of infectious diseases that is caused by Rickettsia. "According to the literature, both TLR2 and TLR4 are known as good Toll-like receptors for interaction in rickettsiosis, however TLR2 could be present a more exacerbated response and cause pathological effects." (PMID 40136144, 2025).
RSV bronchiolitis (1 paper, 2009). "There were only low and similar levels of expression of neutrophil TLR2 in the three groups and of TLR8 mRNA in term infants with RSV bronchiolitis and controls (p>0.05)." (PMID 19497921, 2009).
salivary gland disease (1 paper, 2025). "The knowledge obtained may guide the development of treatment and management strategies for post-COVID-associated salivary gland disease by targeting S protein, its interaction with epithelial cells (e.g., S protein-TLR2/4 axis), and downstream inflammatory cascades." (PMID 41357219, 2025).
Schistosoma haematobium Infection (1 paper, 2008). "Presence of Schistosoma haematobium infection, reported to decrease the risk of atopy and observed in the current study, affected the expression levels of TLR2 and SOCS-3, which were significantly lower in infected children." (PMID 18414649, 2008).
selenium deficiency (1 paper, 2014). A nutritional deficiency disease resulting from inadequate selenium levels in the body, which can lead to impaired function of selenoproteins essential for antioxidant defense and thyroid hormone metabolism. "DNA methylation profile between Keshan Disease patients and normal individuals showed that selenium deficiency decreased methylation of CpG islands in promoter regions of TLR2 and ICAM1, in agreement with results from in vivo and in vitro models of the disease." (PMID 25268836, 2014).
sensitization (1 paper, 2011). "Indeed, TLR2−/− mice developed increased eosinophils and goblet cells in the lung, while TLR4−/− mice did not, suggesting that CP-induced allergic sensitization requires TLR4 but not TLR2." (PMID 21695198, 2011).
severe combined immunodeficiency (1 paper, 2020). Severe combined immunodeficiency (SCID) comprises a group of rare monogenic primary immunodeficiency disorders characterized by a lack of functional peripheral T lymphocytes resulting in early-onset severe respiratory infections and failure to thrive. "On the other hand, inflamed pulp tissues from mice with severe combined immunodeficiency (SCID) have shown a significantly increased expression of TLR‐2 and TLR‐4 (Mutoh, Watabe, Chieda, & Tani‐Ishii, 2009)." (PMID 32400961, 2020).
Shock (1 paper, 2013). The state in which profound and widespread reduction of effective tissue perfusion leads first to reversible, and then if prolonged, to irreversible cellular injury. "Finally, in vivo work demonstrated that HMGB1 contributes to the development of lung injury after severe hemorrhage and that HMGB1-mediated lung inflammation depends on TLR4 in the early phase and on TLR2 in the late phase following hemorrhagic shock." (PMID 23696858, 2013).
sialadenitis (1 paper, 2024). Sialadenitis is an infection of the salivary glands. "A stronger TLR2 or TLR4 expression in IgG4-positive sialadenitis may indicate a tissue-related factor underlying this form of chronic sialadenitis." (PMID 39055281, 2024). "Taken together, these findings support the idea that innate immune responses mediated by TLR2 and/or TLR4 signalling play a role in the overexpression of IgG4-positive plasma cells in IgG4-positive sialadenitis, perhaps through mechanisms similar to those described in true IgG4-RD." (PMID 39055281, 2024). "A strong expression of TLR2 and TLR4 in IgG4-positive forms of sialadenitis may indicate a tissue-related factor as an antigen in this specific form of chronic sialadenitis." (PMID 39055281, 2024). "Thus, the stronger expression patterns of TLR2 and TLR4 we observed in the IgG4-positive group may indicate an aberrant role of TLR-mediated inflammatory responses in IgG4-overexpressing sialadenitis." (PMID 39055281, 2024).
silicosis (1 paper, 2025). Silicosis is a respiratory disease caused by breathing in (inhaling) silica dust. "Mechanistically, PFD appears to mitigate silicosis pathogenesis through suppression of epithelial TLR2/NF-κB pathway activation." (PMID 40470053, 2025). "We found that PFD may alleviate inflammation and fibrosis in silicosis by inhibiting the TLR2/NF-κB pathway in epithelial cells, thereby reducing the production of TNF and MMP9." (PMID 40470053, 2025). "In conclusion, we identified TNF, MMP9, NF-κB1 and TLR2, that contribute to the therapeutic effects of PFD in silicosis." (PMID 40470053, 2025).
skin melanoma (1 paper, 2018). "The aim of this study was to evaluate whether Saccharomyces cerevisiae-derived zymosan-modulated skin melanoma progression by regulation of TLR-2 and TLR-4 expression in peritoneal macrophages and serum TNF-α level." (PMID 29588627, 2018).
spinal cord injury (1 paper, 2012). Penetrating and non-penetrating injuries to the spinal cord resulting from traumatic external forces (e.g., WOUNDS, GUNSHOT; WHIPLASH INJURIES; etc.). "Because TLRs might also have non-immune functions in spinal-cord injury (SCI), we aimed to investigate the influence of TLR2 and TLR4 on synaptic plasticity and glial reactivity after peripheral nerve axotomy." (PMID 23092428, 2012).
synovitis (1 paper, 2025). Inflammation of a synovial membrane. "A plausible explanation for this observation is the potential role of TLR2 and TLR4 signaling in the pathogenesis of synovitis." (PMID 41282165, 2025).
Td (1 paper, 2016). "In all subjects combined, 2 SNPs in TLR1 (−2192T>C, 1805G>T) were significantly associated with Td, and one SNP in TLR2 (597T>C) was significantly associated with BOP." (PMID 27727278, 2016). "In all subjects combined, 2 SNPs in TLR1 were significantly associated with Td, and one SNP in TLR2 was significantly associated with BOP." (PMID 27727278, 2016).
tongue cancer (1 paper, 2020). A malignant neoplasm affecting the tongue. "The nuclear TLR2 expression level can predict tumor recurrence and neck metastases of tongue cancer." (PMID 32424768, 2020).
tongue tumors (1 paper, 2017). "Chronic infection with Porphyromonas gingivalis and Fusobacterium nucleatum has been recently shown to promote tongue tumors in a murine model via direct interaction with oral epithelial cells, leading to upregulation of the IL-6-STAT3 pathway in a TLR2-dependent manner." (PMID 29340028, 2017).
transient cerebral ischemia (1 paper, 2012). "Among diverse TLRs, it has been reported that, after transient cerebral ischemia, induction of TLR2 predominates among TLRs, followed by TLR4 and TLR9." (PMID 22873409, 2012).
tubulointerstitial nephritis (1 paper, 2013). "Instead, activation of TLR2 and TLR4 by LPS on renal epithelial cells is thought to cause tubulointerstitial nephritis." (PMID 23809518, 2013).
vaginitis (1 paper, 2026). A non-infectious or infectious inflammatory process affecting the vagina. "Τhe distribution of TLR2 Arg753Gln and TLR4 Asp299Gly/Thr399Ile polymorphisms in Greek women, including RVVC (n = 63), first-episode VVC (n = 37), Gardnerella vaginalis vaginitis (GV, n = 36) patients, and healthy controls (n = 61), was investigated using TaqMan SNP genotyping." (PMID 41900485, 2026).
valvular heart disease (1 paper, 2011). "In the present study, we also showed the novel association of AF with elevated TLR2 in the RAAs from patients with valvular heart disease." (PMID 23554687, 2011). "In conclusion, we demonstrated that TLR2 was elevated in AF (especially PaAF) patients with valvular heart disease, further implicating inflammation involved in the pathogenesis and development of AF." (PMID 23554687, 2011). "In the present study, we attempted to test our hypothesis that atrial levels of TLR2 were up-regulated to different degrees in paroxysmal AF (PaAF) and persistent AF (PeAF) patients with valvular heart disease." (PMID 23554687, 2011). "In conclusion, TLR2, independent of IL-6, was up-regulated in AF (especially PaAF) patients with valvular heart disease, which further implicates inflammation in the pathogenesis and development of AF." (PMID 23554687, 2011). "TLR2 could be detected in the RAA tissues of AF and SR patients with valvular heart disease." (PMID 23554687, 2011).
Ventricular arrhythmia (1 paper, 2016). "In the absence of TLR2, NLRP3, Caspase 1 or IL-1r, DM fails to sensitize rodents to ventricular arrhythmias." (PMID 27882934, 2016).
Whipple disease (1 paper, 2010). A systemic infection caused by the Gram-positive bacterium Tropheryma whipplei. "TLR2 has been shown to be overexpressed in intestinal lesions of Whipple's disease." (PMID 20090833, 2010).
infection (1,165 papers, 2005 to 2026). The state of being infected such as from the introduction of a foreign agent such as serum, vaccine, antigenic substance or organism. "A study involving 155 patients with infections and 262 healthy controls demonstrated that variants in TLR2 (rs5743708) and TLR4 (rs4986790) are linked to an increased susceptibility to severe infections." (PMID 41170422, 2025). "Bacterial pathogen-associated molecular patterns activate the Tlr2/Tlr4–Myd88 pathway in pathological environments, converting infection signals into bone resorption signals, activating RANKL expression and inducing bone destruction." (PMID 40307566, 2025). "The anticoagulant PROC associated positively with TLR1 and TLR9, but, with infection, became inversely correlated with TLR2, TLR5, and TLR8." (PMID 40825056, 2025). "From the perspective of a host cell, TLR2 and lipoprotein-like lipoproteins have been implicated in the infection process of S. aureus." (PMID 40061451, 2025). "Under in vivo conditions, at 72 hours and 2 weeks post-infection, results regarding IL-10+ MDSCs were similar between WT and TLR2-deficient mice." (PMID 39035356, 2024). "Upon infection with Leishmania ̧ Toll-like Receptors (TLR) including TLR2, 7/8 and 9 recognize various Leishmania pathogen-associated molecular patterns and subsequent TLR activation through upregulation of NF-κB can prime the inflammasome." (PMID 39250503, 2024). "Studies in TLR2 and Mal knock-out mice supported in vitro findings that documented the crucial role of TLR2/Mal-dependent signaling in the increased NF-κB activation caused by LCMV-ARM infection compared to LCMV-WE." (PMID 38675975, 2024). "This systematic review identifies the role of TLR2 during the infection of pathogenic Leptospira spp." (PMID 39729468, 2024). "Mice lacking Nod2 (Nucleotide-binding oligomerization domain-containing protein 2), Myd88 (Myeloid differentiation primary response protein), and Tlr2 (Toll-like receptor 2) are more susceptible to infection with S. aureus than mice expressing these genes." (PMID 39178306, 2024). "Findings concluded that Vaccine I with adjuvant shows higher interactions with TLR2, which suggests that Vaccine I has the ability to induce humoral and cell-mediated responses to treat and to prevent infection caused by S. gordonii." (PMID 39056703, 2024). "We used chemical cross-linking to identify induced interacting partners of TLR2 that contribute to bacterial immune escape, and found that infection induces TLR2 association with vinculin (VCL)." (PMID 37023213, 2023). "Single nucleotide polymorphisms (SNPs) in genes, such as TLR2, responsible for an effective human immune response, can change the course of infection." (PMID 37895256, 2023). "Due to substantial CD4+ T cell loss during infection, mb-TLR2 expression in jejunum CD4+ T cells was excluded from our analysis." (PMID 38140264, 2023). "Despite potential redundancies in Mtb ligand/innate immune receptor interactions during in vivo infection, loss of the TLR2/PIM6 interaction impacted the cellular composition of both the innate and adaptive compartments." (PMID 37439558, 2023). "Surprisingly, in this study, we observed that pregnant mice deficient for both TLR2 and TLR4 (TLR2/4) were able to curtail the ascending infection of a hyaluronidase-proficient WT GBS strain." (PMID 37747229, 2023). "Infection with A. actinomycetemcomitans caused a significant upregulation in the expression levels of Isg15, Mx1, Mx2, Irf3, Irf7, Tlr-2, Tnf-α, Cxcl-1, and Il-6 genes." (PMID 37929187, 2023). "The expression and phosphorylation levels of proteins associated with the TLR2/NFκB signaling pathway in the liver were detected at three, five, and seven days after infection with L. monocytogenes." (PMID 37298614, 2023).